SEC23A (SEC23 homolog A, COPII component)
Diseases named in the same sentence as SEC23A in open-access papers (continued):
Sharing a sentence is not in itself a finding about the gene and the disease.
cancer (continued). "We next evaluated the correlation between SEC23A expression and MEF2A or Hspa12a in Pan-cancer patients and prioritized MEF2A for biological validation." (PMID 34456965, 2021). "It is concerning because recent research has revealed a link between high levels of SEC23A and RSU1 expression and poor prognosis in a number of malignancies, indicating that these proteins may have pro-cancer actions." (PMID 38402311, 2024). "In vivo, the functions of SEC23A and SEC23B have been found to be interchangeable in COPII, whereas SEC23A and SEC23B may have the opposite activity in human cancer for unknown reasons." (PMID 37046730, 2023). "However, additional research is needed to understand the precise function and role of SEC23A and SEC23B in human disease and cancer development." (PMID 31595159, 2019). "This section will discuss the role of SEC23 in human cancer development and progression, although previous studies revealed that SEC23A and SEC23B might have been opposing roles in cancer." (PMID 31595159, 2019).
infection (4 papers, 2015 to 2025). The state of being infected such as from the introduction of a foreign agent such as serum, vaccine, antigenic substance or organism. "Parental HEK293T and CI-M6PR-deficient cells were transiently transfected with a plasmid-expressing GFP-tagged Sec23A followed by infection with wild-type S. Typhi as described in (i)." (PMID 35579416, 2022). "Twenty-four hours after infection, cells were lysed and the interaction between typhoid toxin and Sec23A was probed by immunoprecipitation with anti-FLAG M2 affinity gel and immunoblotting with anti-CdtB and anti-GFP antibodies." (PMID 35579416, 2022). "HEK293T cells transiently transfected with a plasmid-expressing GFP-tagged Sec23A were infected with either wild-type S. Typhi (multiplicity of infection [MOI] = 30) or its isogenic spiA mutant (MOI = 90), which is defective in its SPI-2-encoded type III secretion system." (PMID 35579416, 2022). "Our results also indicated the downregulation of certain proteins after infection with H37Ra such as inactive rhomboid protein 2 (RHBDF2), canopy-2 (CNPY2), hypoxia upregulated protein 1 (HYOU1), and protein transport protein sec23A (SC23A)." (PMID 25785198, 2015). "Vero-E6 cells were transfected with Sec23A or Sec24B small interfering RNA (siRNA), followed by infection with PEDV with or without TSA treatment." (PMID 37766280, 2023).
SEC23A also shares sentences with these, for which no sentence is quoted: craniolenticulosutural dysplasia (3 papers); osteogenesis imperfecta (2); adrenocortical carcinoma (1); Ataxia (1); bladder urothelial carcinoma (1); cardiomyopathy (1); chylomicron retention disease (1); congenital dyserythropoietic anemia (1); diabetes (1); genetic disorder (1); glioma (1); hepatocellular carcinoma (1); iron overload (1); lymph node metastasis (1); Marinesco-Sjögren Syndrome (1); myopathy (1); neurodegenerative disease (1); osteosarcoma (1); retinal degeneration (1); Stomach Adenocarcinoma (1).